COL24A1 (collagen type XXIV alpha 1 chain)
Description:
May participate in regulating type I collagen fibrillogenesis at specific anatomical locations during fetal development.
Tractability: Antibody: its Gene Ontology location is reachable by antibodies, with high confidence; UniProt places it where antibodies can reach, with medium confidence; UniProt predicts a signal peptide or a membrane-spanning region. PROTAC: ubiquitination databases record sites on it. Other modalities: an approved drug acts on it.
Gene: Protein-coding gene on chromosome 1 (85,729,233 to 86,156,943, reverse strand). Ensembl gene ENSG00000171502.
Subcellular location: Secreted, extracellular space, extracellular matrix
Pathways (Reactome):
Extracellular matrix organization: Assembly of collagen fibrils and other multimeric structures; Collagen biosynthesis and modifying enzymes; Collagen chain trimerization
Developmental Biology: Developmental Lineage of Pancreatic Ductal Cells
Signal Transduction: MET activates PTK2 signaling
Gene Ontology:
Molecular function: protein binding; extracellular matrix structural constituent conferring tensile strength; extracellular matrix structural constituent
Biological process: extracellular matrix organization
Cellular component: extracellular matrix; basement membrane; collagen type XXIV trimer; endoplasmic reticulum lumen; extracellular region
Genetic constraint (gnomAD): Loss-of-function variants: 145 observed, 174.13 expected, observed/expected ratio (o/e) 0.83, 90% interval 0.73 to 0.96. The upper end of that interval is the gene's LOEUF score, 0.96, which puts it in group 4 of 6, group 1 being the genes least tolerant of losing a copy. Missense variants: 1,682 observed, 1,734.7 expected, observed/expected ratio (o/e) 0.97, 90% interval 0.93 to 1.01. Synonymous variants: 557 observed, 572.94 expected, observed/expected ratio (o/e) 0.97, 90% interval 0.91 to 1.04.
Homologues: Orthologues: chimpanzee COL24A1 (99% identical), macaque COL24A1 (96% identical), rabbit COL24A1 (85% identical), guinea pig COL24A1 (76% identical), pig COL24A1 (75% identical). Paralogues in human: COL27A1 (42% identical), COL11A1 (37% identical), COL5A1 (37% identical), COL5A3 (35% identical), COL11A2 (34% identical), COL2A1 (29% identical), COL1A1 (28% identical), COL5A2 (28% identical), COL3A1 (28% identical), COL4A5 (28% identical), COL4A1 (27% identical), COL1A2 (27% identical), and 25 more.
Diseases named in the same sentence as COL24A1 in open-access papers:
COL24A1 is named in the same sentence as 25 diseases in open-access papers, as found by Europe PMC text mining. Sharing a sentence is not in itself a finding about the gene and the disease. The quoted sentences say what the papers report.
glioma (2 papers, 2024 to 2025). A benign or malignant brain and spinal cord tumor that arises from glial cells (astrocytes, oligodendrocytes, ependymal cells). "Interestingly, the only differentially expressed collagen gene (COL24A1) showed decreased transcript abundance in perivascular cells of the grade 2 glioma sample." (PMID 41366031, 2025).
Obesity (2 papers, 2017 to 2023). Accumulation of substantial excess body fat. "Here, Hong and colleagues perform a genome-wide gene × environment interaction analysis and find that maternal COL24A1 variants have a significant interaction with maternal pre-pregnancy obesity in increasing PTB risk." (PMID 28598419, 2017). "We show that maternal COL24A1 variants have a significant genome-wide interaction with maternal pre-pregnancy overweight/obesity on PTB risk, with rs11161721 (PG × E=1.8 × 10−8; empirical PG × E=1.2 × 10−8) as the top hit." (PMID 28598419, 2017). "We looked for common genes between the up-DPpGCs in TS and TA, and the significant differentially expressed genes (DEGs) induced by exercise in SkM of old mice, and found four genes, ATP1A3, SLC17A7, SYN2, and COL24A1 from the up-DPpGCs in TS, that are related to neurotransmission and obesity." (PMID 36769072, 2023).
breast carcinoma (1 paper, 2014). "Interestingly, expression of KLK5 was high in basal-like and normal-like breast cancer subtypes with a reduction in levels in luminal B. There was reduced expression in normal tissue and basal subtypes with higher expression in luminal (ER+) and Her-2 subtypes for ITGB5, EZR, COL12A1, and COL24A1." (PMID 25593998, 2014).
cardiomyopathies (1 paper, 2025). "TTN variants are associated with myopathies, muscular dystrophies, and cardiomyopathies (OMIM 188840), which are inconsistent with the phenotypes of these probands, and COL24A1 variants have not been associated with Mendelian phenotypes." (PMID 40662098, 2025).
head and neck cancer (1 paper, 2023). A primary or metastatic malignant neoplasm affecting the head and neck. "COL24A1 is an ECM component shown previously to be overexpressed in hepatocellular carcinoma and head and neck cancer; in both malignancies, its expression correlated with poor prognosis." (PMID 37686244, 2023).
joint disease (1 paper, 2019). "Therefore, collagen dysfunction could lead to bone and joint disease including OA.COL24A1, COL5A2, COL3A1, COL6A1 are members of the collagen gene family." (PMID 30941059, 2019).
leiomyoma (1 paper, 2019). A well-circumscribed benign smooth muscle neoplasm characterized by the presence of spindle cells with cigar-shaped nuclei, interlacing fascicles, and a whorled pattern. "They identified several proteins up regulated in the leiomyoma: POSTN, TNC, COL3A1, COL24A1, and ASPN." (PMID 31100862, 2019).
tumor (3 papers, 2014 to 2022). "Accordingly, hyperacetylation/upregulation of oncogenes related with angiogenesis and vascular invasion (COL24A1, NDP and HOXA13) and hypoacetylation/downregulation of angiogenesis-tumor suppressor genes (CD40 and IL15) was identified in this study." (PMID 35740301, 2022).
COL24A1 also shares sentences with these, for which no sentence is quoted: cancer (1 paper); co-infection (1); Ehlers-Danlos syndrome (1); epilepsy (1); gastric cancer (1); Hallux valgus (1); Hepatic fibrosis (1); hepatocellular carcinoma (1); infection (1); ischemia (1); ischemic stroke (1); lung adenocarcinoma (1); muscular dystrophies (1); myopathies (1); ovarian carcinoma (1); pulmonary fibrosis (1); Sepsis (1).